RAP1GAP (RAP1 GTPase activating protein)
Description:
GTPase activator for the nuclear Ras-related regulatory protein RAP-1A (KREV-1), converting it to the putatively inactive GDP-bound state.
Synonyms: Rap1GAP1; KIAA0474; RAP1GA1; RAP1GAPII; RAPGAP
Tractability: Small molecule: a structure with a bound ligand is known; it has a high-quality binding pocket. Antibody: UniProt places it where antibodies can reach, with medium confidence. PROTAC: ubiquitination databases record sites on it; its protein half-life has been measured.
Gene: Protein-coding gene on chromosome 1 (21,596,215 to 21,669,846, reverse strand). Ensembl gene ENSG00000076864.
Subcellular location: Golgi apparatus membrane
Subcellular location (Human Protein Atlas): Cytosol
Pathways (Reactome):
Developmental Biology: RET signaling
Immune System: Rap1 signalling
Gene Ontology:
Molecular function: GTPase activator activity; protein binding; protein homodimerization activity; small GTPase binding; GTPase activity; GTPase regulator activity
Biological process: negative regulation of microvillus assembly; positive regulation of GTPase activity; regulation of GTPase activity; adaptive immune response; regulation of cell-cell adhesion; signal transduction; cellular response to glial cell derived neurotrophic factor; negative regulation of neuron differentiation; negative regulation of thyroid gland epithelial cell proliferation; regulation of small GTPase mediated signal transduction
Cellular component: cytosol; membrane; axon; plasma membrane; dendrite; early endosome; Golgi membrane; neuronal cell body
Genetic constraint (gnomAD): Loss-of-function variants: 34 observed, 76.4 expected, observed/expected ratio (o/e) 0.45, 90% interval 0.34 to 0.59. The upper end of that interval is the gene's LOEUF score, 0.59, which puts it in group 2 of 6, group 1 being the genes least tolerant of losing a copy. Missense variants: 733 observed, 841.71 expected, observed/expected ratio (o/e) 0.87, 90% interval 0.82 to 0.93. Synonymous variants: 375 observed, 338.41 expected, observed/expected ratio (o/e) 1.11, 90% interval 1.02 to 1.21.
Homologues: Orthologues: macaque RAP1GAP (99% identical), pig RAP1GAP (98% identical), guinea pig RAP1GAP (97% identical), rat Rap1gap (97% identical), mouse Rap1gap (97% identical), dog RAP1GAP (94% identical), rabbit RAP1GAP (88% identical), zebrafish rap1gapa (78% identical), zebrafish rap1gapb (75% identical), chimpanzee RAP1GAP (74% identical), Drosophila melanogaster RapGAP1 (44% identical), Caenorhabditis elegans F53A10.2 (40% identical). Paralogues in human: RAP1GAP2 (53% identical), SIPA1L3 (35% identical), SIPA1L2 (34% identical), SIPA1L1 (33% identical), SIPA1 (27% identical), GARNL3 (26% identical).
Diseases named in the same sentence as RAP1GAP in open-access papers:
RAP1GAP is named in the same sentence as 44 diseases in open-access papers, as found by Europe PMC text mining. Sharing a sentence is not in itself a finding about the gene and the disease. The quoted sentences say what the papers report.
melanoma (9 papers, 2012 to 2025). A malignant, usually aggressive tumor composed of atypical, neoplastic melanocytes. "Accordingly, a clinicopathological study reported that high Rap1GAP expression might be a useful marker to identify high-risk melanoma." (PMID 22535842, 2012). "Consistent with its ability to inactivate RAP1, RAP1GAP is a tumor suppressor in several human cancers, including endometrial, thyroid, pancreas, colon, melanomas, prostate, and head and neck carcinomas." (PMID 34593556, 2021). "RAP1GAP downregulation via promoter hypermethylation was reported to promote the cell proliferation, survival, and migration of melanoma cells." (PMID 32641122, 2020). "In melanoma and renal cell carcinoma, Rap1GAP downregulation was mediated through promoter hypermethylation." (PMID 32906721, 2020). "Rap1GAP has been shown to be frequently suppressed in malignant melanoma via promoter hypermethylation, which promoted melanoma cell proliferation, survival and migration." (PMID 28009991, 2017). "Lower or lost expression of Rap1GAP has been reported in pancreatic cancer, thyroid tumors and melanoma." (PMID 28009991, 2017). "Genes deregulated at the DNA and mRNA level included well-known cancer genes partly already linked to melanoma (RAS genes, PTEN, AURKA, MAPK inhibitors Sprouty/Spred), but also novel candidates like SIPA1 (a Rap1GAP)." (PMID 22535842, 2012). "Furthermore, miR-31 overexpression resulted in down-regulation of EZH2 and a de-repression of its target gene rap1GAP; increased expression of EZH2 was associated with melanoma progression and overall patient survival." (PMID 22948084, 2012). "Rap1GAP is a critical tumor suppressor gene that is downregulated in multiple cancers such as prostate cancer, breast cancer, oropharyngeal squamous cell carcinoma, pancreatic cancer, thyroid carcinoma, melanoma, colorectal cancer, B-cell lymphomas, kidney cancer, and acute myeloid leukemia." (PMID 28009991, 2017). "NRAS Q61L melanomas were most enriched for modules 7 (C19orf10, ARF4, KDELR2), 13 (TIMM50, ZBED3-AS1, SERPINF1), and 15 (RAP1GAP, OCA2, PAICS)." (PMID 39796775, 2025). "One such potential tumor suppressor is Rap1GAP, which converts active Rap1-GTP to inactive Rap1-GDP, and is deleted in a number of cancers, including melanoma." (PMID 23056350, 2012).
thyroid cancer (6 papers, 2017 to 2025). "Pancreatic cancer and thyroid cancer studies demonstrate that the loss of Rap1GAP activity was associated with a high frequency of LOH of the Rap1GAP gene." (PMID 32906721, 2020). "For instance, Matrilin 2 (MATN2) and Rap1-GTPase activating protein 1 (RAP1GA1) were notably underexpressed in thyroid carcinoma samples." (PMID 40346322, 2025). "In thyroid carcinoma cells, Rap1GAP expression was abolished by Ras transformation, promoter hypermethylation and loss of heterozygosity, and the downregulation of Rap1GAP promoted cell proliferation, migration and invasion." (PMID 28009991, 2017). "In addition, the upregulation of Rap1GAP in thyroid carcinoma cells impaired cytoskeletal remodeling and migration via Src/FAK signaling." (PMID 32906721, 2020). "Rap1GAP regulates the specific GAP activity for Rap1 and is known as a tumor suppressor gene and plays a key role in human tumor progression including thyroid cancer." (PMID 34840979, 2021). "Additionally, by combining DNA methylation with gene expression data, we further found a relationship between the expression and methylation level in some genes, such as RAP1GAP and BMP8A, which proved to play a role in the progression of thyroid cancer." (PMID 36612238, 2022). "Rap1GAP expression was selectively suppressed in human thyroid carcinoma cell lines that neither unfolded an epithelial morphology nor expressed E-cadherin." (PMID 28009991, 2017).
thyroid tumor (5 papers, 2015 to 2024). A benign or malignant neoplasm affecting the thyroid gland. "Tumor suppressor gene RAP1GAP, which is inactivated by hypermethylation of its regulatory region, can cause thyroid tumor." (PMID 38685045, 2024). "In thyroid tumour cell lines, the immunohistochemistry studies showed RAP1GAP gene downregulation in PTC along with its invasion and proliferation." (PMID 39558949, 2024). "The depletion of Rap1GAP in thyroid tumors may enhance Src kinase activity, thereby promoting skeletal remodeling and motility in cancer cells, which may well explain our results." (PMID 34840979, 2021). "This is consistent with findings in human thyroid tumors where downregulation of Rap1GAP expression promoted aberrant cell migration and invasion, which could be restored back to normal upon re-expression of RAP1GAP." (PMID 26300785, 2015).
colorectal cancer (4 papers, 2020 to 2024). A primary or metastatic malignant neoplasm that affects the colon or rectum. "A downregulation of Rap1GAP in colorectal cancer patients was associated with increased MMP9 expression and poorer survival rates." (PMID 32906721, 2020). "Recent study showed that upregulation of Rap1GAP was positively associated with the expression of E-cadherin in gastric cancer and colorectal cancer." (PMID 32906721, 2020). "Colorectal cancer cell proliferation, migration, and invasion can be effectively suppressed by inhibiting the expression of Rap1GAP." (PMID 38448739, 2024). "Previous reports on gastric cancer and colorectal cancer reckoned RAP1GAP as a tumor suppressor gene." (PMID 37919693, 2023). "The importance of Rap1GAP in cell–cell adhesion is also reported in research on carcinoma cells: deletion of Rap1GAP prevented the formation of adherens junctions in colorectal carcinoma indicating that Rap1GAP is necessary for the formation of adherens junctions at a basal level." (PMID 35054818, 2022).
gastric cancer (4 papers, 2017 to 2023). A primary or metastatic malignant neoplasm involving the stomach. "Rap1GAP is a crucial tumor suppressor, but its role in gastric cancer (GC) is little investigated." (PMID 28009991, 2017). "The expression of Rap1 GTPase activating protein (RAP1GAP) was downregulated in gastric cancer, but the difference was not statistically significant." (PMID 34249673, 2021).
pancreatic cancer (4 papers, 2017 to 2024). "Both in vivo and in vitro studies clearly showed that induced expression of Rap1GAP was associated with the decreased of pancreatic cancer growth, motility and invasiveness." (PMID 32906721, 2020). "In vitro and in vivo studies showed that loss of Rap1GAP promotes pancreatic cancer growth, survival, and invasion, and may function through modulation of integrin activity." (PMID 30241315, 2018). "Immunohistochemical staining revealed that Rap1GAP expression is greatly reduced in poorly differentiated pancreatic cancer as compared to normal pancreatic tissues or chronic pancreatitis." (PMID 32906721, 2020). "The overexpression of Rap1GAP in pancreatic cancer cells enhances the basal apoptotic rates and increases drug sensitivity such as 5-fluorouracil (5-FU) and etoposide." (PMID 32906721, 2020). "Rap1GAP was identified as a putative tumor suppressor gene in pancreatic cancer where studies showed that expression of Rap1GAP was significantly downregulated." (PMID 30241315, 2018). "LOH for Rap1GAP gene induced tumor growth, invasion, and survival in pancreatic cancer." (PMID 32906721, 2020). "Moreover, Rap1GAP-overexpressing pancreatic cancer cells treated with apoptosis-inducing chemotherapeutic drugs, such as 5-FU and etoposide, induced up to 28% (5-FU) and 13% (etoposide) higher rates of apoptosis in comparison to control cells." (PMID 30241315, 2018). "We established and validated a prognostic model for pancreatic cancer with 7 signatures, including ADH1C, APOE, RAP1GAP, NPC1L1, P4HB, SOD2, and TNFSF10." (PMID 38685045, 2024).
breast carcinoma (3 papers, 2012 to 2021). "In breast cancer, genomic mutation of Rap1GAP plays an important role in cancer progression." (PMID 28009991, 2017). "Next, RNA and protein expression of CCND3, DUSP10 and RAP1GAP was evaluated on breast cancer cell lines with known gene expression data to assess the correlation between gene and protein expression of these genes." (PMID 34440000, 2021).
squamous cell carcinoma (3 papers, 2017 to 2024). A carcinoma arising from squamous epithelial cells. "Rap1 signaling, Rap1, and Rap1GAP are known to play a role in the progression of squamous-cell carcinoma of the head and neck." (PMID 29156751, 2017). "However, other investigations have demonstrated that RAP1GAP can promote the invasion and migration of squamous cell carcinoma cells and myeloid leukemia cell lines." (PMID 37919693, 2023).
colitis (2 papers, 2018 to 2024). Inflammation of the colon. "In summary, PN could downregulate increased VEGFA121 and VEGFA165 and block Rap1GAP/TSP1 signaling pathway in experimental colitis so that it attenuates microvascular injury, which resulted in improving repair of mucosal injury." (PMID 29785192, 2018). "The expression of Rap1GAP and TSP1 proteins was significantly increased in IA- and DSS-induced experimental colitis groups compared with the normal control group." (PMID 29785192, 2018). "In the study, the expression of Rap1GAP and TSP1 proteins was significantly downregulated by PN in colonic mucosa with the microvascular injury decreased in the rats with colitis." (PMID 29785192, 2018). "After treatment by PN, the expression of Rap1GAP and TSP1 proteins in colonic mucosa was reversed in the rats with colitis." (PMID 29785192, 2018).
head and neck squamous cell carcinoma (2 papers, 2017 to 2025). A squamous cell carcinoma that arises from any of the following anatomic sites: lip and oral cavity, nasal cavity, paranasal sinuses, pharynx, larynx, and salivary glands. "In head and neck squamous cell carcinoma, Rap1GAP is repressed via EZH2, itself regulated by miR-101 and miR-26a, linking Rap1 to tumor invasion through a miR-101 → EZH2 → Rap1GAP → Rap1 axis." (PMID 40508181, 2025). "However, in head and neck squamous cell carcinoma, Rap1GAP promotes invasion via induction of MMP9 secretion." (PMID 28009991, 2017). "In the head and neck squamous cell carcinoma (SCC), EZH2 repressed Rap1GAP by facilitating the trimethylationof H3K27 and hypermethylation of the Rap1GAP promoter, and the downregulation of Rap1GAP activated the activity of Rap1, and eventually promoted proliferation and invasion." (PMID 28009991, 2017).
leukemia (2 papers, 2017 to 2022). A malignant (clonal) hematologic disorder, involving hematopoietic stem cells and characterized by the presence of primitive or atypical myeloid or lymphoid cells in the bone marrow and the blood. "In myeloid leukemia cell lines, Rap1GAP promotes leukemia cell differentiation and apoptosis, but increases leukemia cell invasion in vitro by the upregulation of MMP9." (PMID 28009991, 2017).
Obesity (2 papers, 2019 to 2022). Accumulation of substantial excess body fat. "Previous studies have found that overexpression of RAP1GAP has a negative regulatory effect on Rap1, which can enhance the cellular effect of leptin and reduce the production of obesity." (PMID 36090178, 2022).
renal cell carcinoma (2 papers, 2017 to 2020). "Rescued expression of Rap1GAP in renal cell carcinoma cell lines using a demethylating drug, decitabine (5-azadC), resulted in a significant reduction in tumor invasiveness." (PMID 32906721, 2020). "The low expression levels of Rap1GAP in renal cell carcinoma cells was partly due to promoter hypermethylation, and attenuated the invasion of kidney cancer cells." (PMID 28009991, 2017).
thyroid (2 papers, 2012 to 2013). "Regarding the selected genes in other CNA/UPD areas, the AKT3/PIK3CA pathway, the KRAS/RAP1B/RAP1GAP/BRAF pathway, and the VEGFC pathway have been known to participate in thyroid carcinogenesis/cancer progression." (PMID 22558328, 2012).
adenovirus infection (1 paper, 2021). "In the experiment of mRFP-GFP-LC3 adenovirus infection, compared with the si-control group, Rap1GAP knockdown increased the red dots and decreased the merged yellow spots, and the binding of autophagosomes to lysosomes was blocked." (PMID 33936386, 2021).
cardiac hypertrophy (1 paper, 2021). "We measured the cardiac Rap1GAP protein and mRNA levels in the cardiac hypertrophy model compared to the control rats." (PMID 33936386, 2021).
cervical cancer (1 paper, 2021). A primary or metastatic malignant neoplasm involving the cervix. "The expression of Rap1GAP was found to be decreased in cervical cancer tissues and was negatively correlated with HPV16/18 infection." (PMID 34952616, 2021). "The molecular mechanism through which HPV affects Rap1GAP degradation and its roles in cervical cancer development deserves further analysis." (PMID 34952616, 2021). "Previous studies have revealed that down-regulation of Rap1GAP is correlated with HPV16/18 infection in cervical cancer." (PMID 34952616, 2021). "Rap1GAP, a key molecule that regulates the activity of Rap1, was found to be down-regulated in cervical cancer with HPV16/18 infection." (PMID 34952616, 2021). "In our previous studies on cervical cancer, we found that Rap1GAP inhibits the migration and invasion of cervical cancer cells." (PMID 34952616, 2021). "In this study, we aimed to address the degradation pathway of Rap1GAP in HPV-positive cervical cancer cells." (PMID 34952616, 2021). "Rap1GAP may be degraded by autophagy in cervical cancer cells, but HPV infection can switch the degradation pathway from autophagy to E6AP-mediated ubiquitin-proteasome degradation." (PMID 34952616, 2021). "Because the ubiquitin-mediated degradation of Rap1GAP was found to be HR HPV16/18-dependent, we analyzed the interaction between Rap1GAP and E6AP using co-IP assays in HPV-positive cervical cancer cells." (PMID 34952616, 2021). "HPV-positive (HeLa and SiHa) and negative (C33A) cervical cancer cells were used to analyze the pathways of Rap1GAP degradation." (PMID 34952616, 2021). "Treatment of the cells with MG132 led to an increase in the protein levels of Rap1GAP in the HPV-positive cervical cancer cells, HeLa and SiHa, but not in the HPV-negative cervical cancer cell line, C33A." (PMID 34952616, 2021).
colon cancer (1 paper, 2022). "As a negative regulator for the activation of both Rap1 and Rap2, Rap1GAP down-regulation in colon cancer cells inhibited the formation of adherens junction between cells but enhanced the adhesion of cells and extracellular matrix." (PMID 35054818, 2022).
COVID-19 (1 paper, 2022). A disease caused by infection with severe acute respiratory syndrome coronavirus 2. "The top up-regulated genes after exposure to COVID-19 during pregnancy included ras-associated protein-1 GTPase-activating-protein (RAP1GAP), pro-platelet basic protein (PPBP), and histone cluster 1, H1b (HIST1H1B)." (PMID 35547542, 2022).
endometrioid adenocarcinoma (1 paper, 2024). An adenocarcinoma characterized by the presence of malignant glandular epithelial cells resembling endometrial cells. "The silencing of RAP1GAP promotes endometrioid adenocarcinoma cell migration and invasion." (PMID 38685045, 2024).
endometriosis (1 paper, 2021). The growth of functional endometrial tissue in anatomic sites outside the uterine body. "This study revealed that gut-derived n-butyrate protects against endometriosis by activating the expression of RAP1GAP GTPase to inhibit the RAP1 oncogenic pathway, indicating n-butyrate is linked with intestinal microbiota and endometriosis disease." (PMID 34593556, 2021).
focal and segmental glomerulosclerosis (1 paper, 2015). "Increased expression of Rap1GAP was also detected in kidney samples obtained from patients with focal and segmental glomerulosclerosis (FSGS)." (PMID 26300785, 2015).
glomerular disease (1 paper, 2022). "Decreased RAP1-GTP mediated by elevated RAP1GAP levels may be a crucial factor in inducing podocyte dysfunction in human glomerular disease." (PMID 36209090, 2022).
influenza (1 paper, 2024). An acute viral infection of the respiratory tract, occurring in isolated cases, in epidemics, or in pandemics; it is caused by serologically different strains of viruses (influenzaviruses) designated A, B, and C, has a 3-day incubation period, and usually lasts for 3 to 10 days. "In contrast, PCOLCE2, TDRD9, MPO, MAOA, RAP1GAP, and S100P expression was higher in the severe influenza group compared to the non-severe influenza group in the training cohort, similar to the findings in the validation cohort." (PMID 38454348, 2024). "The ten common DEGs (PCOLCE2, HLA_DPA1, LOC653061, TDRD9, MPO, HLA_DQA1, MAOA, S100P, RAP1GAP, and CA1) that were obtained by overlapping genes from computing the three algorithms [LASSO regression, SVM-RFE algorithms, and RF are candidate key genes for severe influenza." (PMID 38454348, 2024).
lung carcinoma (1 paper, 2025). "Mechanistically, CUMS downregulated Rap1GAP, activating Rap1 and subsequent ERK1/2 phosphorylation, thereby promoting EMT in lung cancer tissues." (PMID 40786046, 2025).